GRHL3 (grainyhead like transcription factor 3)
Diseases named in the same sentence as GRHL3 in open-access papers (continued):
Sharing a sentence is not in itself a finding about the gene and the disease.
bladder cancer (4 papers, 2021 to 2025). "In conclusion, our comprehensive expression data of GRHL3 in different bladder cancer subtypes are associated with distinct prognostic implications." (PMID 38429970, 2024). "In this study, we investigated the impact of GRHL3 in the proliferation, migration and invasion of urothelial cells by gain- and loss-of-function assays in bladder cancer cell lines." (PMID 33803949, 2021). "Since a reverse GRHL3 expression was revealed for squamous and urothelial bladder cancers, we aimed to analyze the functional role of GRHL3 in different bladder cancer subtypes in vitro." (PMID 38429970, 2024). "A decisive role of GRHL3 in tumor development is also attributed to cell adhesion as demonstrated in our bladder cancer models." (PMID 38429970, 2024). "Subtype‐specific GRHL3 mRNA expression was confirmed in an independent bladder cancer data set of The Cancer Genome Atlas (TCGA)." (PMID 38429970, 2024). "In bladder cancer, the role of GRHL3 is less well known, especially in the context of molecular and histological subtypes." (PMID 38429970, 2024). "In order to assess its potential role in bladder cancer, we generated T24-GRHL3 (T24 + GRHL3) cells by ectopic stable expression using lentiviral vectors." (PMID 33803949, 2021). "In order to understand the contribution of GRHL3 in bladder cancer cells, we next determined its mRNA levels in three bladder cancer cell lines by semi-quantitative RT-PCR." (PMID 33803949, 2021). "In summary, our study shows convincing experimental evidence for an involvement of GRHL3 in bladder cancer cell invasion and differentiation, acting as a potential tumor suppressor protein." (PMID 33803949, 2021). "In contrast, GRHL3 expression was undetectable in the poorly differentiated, invasive bladder cancer cell line T24, assessed by RT-PCR." (PMID 33803949, 2021). "The data presented in this study indicate a role of GRHL3 in the process of invasion during bladder cancer progression." (PMID 33803949, 2021). "Differential expression of GRHL3 was assessed in normal human urothelium and in non-invasive and invasive bladder cancer cell lines." (PMID 33803949, 2021). "We examined GRHL3 mRNA and protein expression in cohorts of patient samples, its prognostic role and its functional impact on tumorigeneses in different molecular and histopathological subtypes of bladder cancer." (PMID 38429970, 2024). "Thus, our study along with prior research efforts gain further insights into role of GRHL3 transcription factor helping to further decipher the clinically important pathways of bladder cancer subtypes." (PMID 38429970, 2024). "Thus, our data provide for the first time a detailed insight into the role of the transcription factor GRHL3 in different histopathological subtypes of bladder cancer." (PMID 38429970, 2024). "Loss of GRHL3 expression may indicate a potential contribution of GRHL3 to bladder cancer progression." (PMID 33803949, 2021). "The functional role of GRHL3 in bladder cancer has been elusive." (PMID 33803949, 2021). "GRHL3 impairs migration and invasion of bladder cancer cells, but does not influence their proliferation rate." (PMID 35269877, 2022). "In bladder cancer cell lines with de novo expression or knockdown of GRHL3, we have not observed differences in E-cadherin expression (not shown)." (PMID 33803949, 2021). "Apart from that, no further studies of GRHL3 in bladder cancer have been described so far, and the role of GRHL3 in sq‐BLCA remains unknown." (PMID 38429970, 2024).
psoriasis (4 papers, 2013 to 2021). An autoimmune condition characterized by red, well-delineated plaques with silvery scales that are usually on the extensor surfaces and scalp. "A number of the SEs with the highest number of GRHL3 peaks overlap genes linked to psoriasis, like IL17C, providing further insight into the role of GRHL3 in psoriasis." (PMID 28445475, 2017). "The role of inflammatory mediators in skin disorders has been well described, but more specifically the effects of deleting GRHL3 in skin has been linked to the initiation and progression of hyperproliferative skin conditions such as psoriasis by interleukin mediated T-cell activation." (PMID 30341279, 2018). "GRHL3 expression was considered to be related to psoriasis-related cytokine activity in human psoriasis lesions." (PMID 34888136, 2021). "Nevertheless, 7 of the PP-increased DEGs were associated with psoriasis susceptibility loci (LCE3D, IFIH1, GRHL3, IL12B, PRSS53, REL and NOS2), and 1 PP-decreased DEG was near a psoriasis susceptibility locus (SDC4)." (PMID 24260178, 2013).
skin cancer (4 papers, 2014 to 2022). "The molecular mechanism underlying the role of GRHL3 in skin cancer is dependent on direct regulation of expression of tumor suppressor PTEN by GRHL3." (PMID 24586629, 2014). "To clarify these apparent discrepancies on the role of IRF6 and GRHL3 in cancer, we screened breast, colon, lung, and skin cancer cell lines for IRF6, GRHL3, and CDH1 transcripts and compared their levels to them in corresponding control cell lines by qPCR." (PMID 36457487, 2022). "In our previous publication we described links between the GRHL3 transcription factor and skin cancer." (PMID 24586629, 2014). "In human skin tumors both GRHL3 and PTEN are regulated by micro RNA miR-21." (PMID 24586629, 2014). "It is thus likely that, in the context of human NMSC, the expression of both GRHL1 and GRHL3 must be simultaneously reduced to delay epidermal cells differentiation and/or induce tumor promoting inflammatory microenvironment in the skin, which would enable skin tumor progression." (PMID 29301499, 2018). "While for certain cancer types (e.g., skin cancer) the roles of IRF6 and GRHL3 were found to be consistent (tumor suppressors), the findings were more controversial in others (e.g., female tissues)." (PMID 36457487, 2022).
colorectal cancer (2 papers, 2021 to 2024). A primary or metastatic malignant neoplasm that affects the colon or rectum. "We explored the underlying mechanism of tumor-promoting effect of GRHL3 in colorectal cancer (CRC), which is involved in the MEK1/2 pathway." (PMID 34888136, 2021). "We found higher GRHL3 expression in colorectal cancer, which was negatively correlated with patients' prognosis." (PMID 34888136, 2021). "Our results suggested that GRHL3 may act as an oncogene to promote tumor growth and metastasis via the MEK pathway in colorectal cancer." (PMID 34888136, 2021).
diabetes (2 papers, 2017 to 2021). "Among nutritional factors, inositol deficiency causes cranial NTDs in mice while supplemental inositol prevents spinal and cranial NTDs in the curly tail (Grhl3 hypomorph) mouse, rodent models of hyperglycemia or induced diabetes, and in a folate‐deficiency induced NTD model." (PMID 27324558, 2017).
head and neck squamous cell carcinoma (2 papers, 2020 to 2022). A squamous cell carcinoma that arises from any of the following anatomic sites: lip and oral cavity, nasal cavity, paranasal sinuses, pharynx, larynx, and salivary glands. "GRHL3 is a potent tumour-suppressor gene, and is implicated in numerous cancers of epithelial origin, such as head and neck squamous cell carcinoma, breast and skin." (PMID 35269877, 2022). "The downregulated GRHL3 gene was associated with head and neck squamous cell carcinomas; overexpression of the oncogenic mir21 was as result of decreased GRHL3." (PMID 32850691, 2020). "The results of studies carried out in both mouse models and human patients indicate that GRHL3 acts as a tumor suppressor in head and neck squamous cell carcinoma (HNSCC)." (PMID 35269877, 2022).
lymph node metastases (2 papers, 2021 to 2024). "GRHL3 may be a strong independent survival predictor according to the multivariate Cox proportional hazards model including gender, age, tumor size, differentiation, invasion depth, TNM stage, lymph node metastasis, and GRHL3 expression." (PMID 34888136, 2021). "GRHL3 has an enhanced expression in CRC; also, high expression of GRHL3 was notably correlated with tumor size, TNM staging, invasion degree, and lymph node metastasis, which suggested that high expression of GRHL3 might tend to correlate with the severity of CRC malignancy potentially." (PMID 34888136, 2021).
papilloma (2 papers, 2017 to 2018). A benign epithelial neoplasm that projects above the surrounding epithelial surface and consists of villous or arborescent outgrowths of fibrovascular stroma. "Grhl3–/– grafts further presented with strong hyperkeratinisation with expansion of Keratin 14 above the basal layer, both apparent hallmarks of papilloma or pre-malignant SCC." (PMID 30341279, 2018). "Furthermore, when mice lacking Grhl3 are left to age without DMBA/TPA administration, they all develop epidermal hyperplasia and spontaneous papillomas, some of which eventually progress to SCC." (PMID 28654000, 2017).
skin squamous cell carcinoma (2 papers, 2016 to 2021). A carcinoma arising from the squamous cells of the epidermis. "In skin squamous cell carcinoma, GRHL3 functioned as a tumor suppressor gene by activating PTEN expression." (PMID 33931584, 2021). "Mice subcutaneously injected with transformed keratinocytes lacking Grhl3 demonstrated increased tumorigenesis, suggesting that decreased Grhl3 expression contributes to tumour progression and up‐regulation of the oncomir miR‐21 in squamous cell carcinoma of the skin." (PMID 26508273, 2016).
triple-negative breast carcinoma (2 papers, 2021 to 2025). An invasive breast carcinoma which is negative for expression of estrogen receptor (ER), progesterone receptor (PR), and human epidermal growth factor receptor 2 (HER2). "GRHL3 was higher when compared to the other pathological cancer types but lower in triple-negative breast cancer." (PMID 34888136, 2021).
urothelial carcinoma (2 papers, 2021 to 2024). A malignant neoplasm derived from the transitional epithelium of the urinary tract (urinary bladder, ureter, urethra, or renal pelvis). "We stably overexpressed GRHL3 in urothelial EJ28 and the basal/squamous SCaBER cell lines and extended with a second model for invasive urothelial carcinomas by overexpressing GRHL3 in urothelial stable J82 pools." (PMID 38429970, 2024). "In contrast, urothelial carcinomas remained GRHL3 mRNA expression (median FC = 0.82) when compared to NU." (PMID 38429970, 2024). "Here, we analyzed the subtype‐specific role of GRHL3 in bladder carcinogenesis, comparing common urothelial carcinoma (UC) with squamous bladder cancer (sq‐BLCA)." (PMID 38429970, 2024). "GRHL3 expression was detectable in normal human urothelial cells and showed significantly higher mRNA and protein levels in well-differentiated, non-invasive RT4 urothelial carcinoma cells compared to moderately differentiated RT112 cells." (PMID 33803949, 2021).
acute myeloid leukaemia (1 paper, 2025). "As previously reported, APOBEC3A was also highly expressed in acute myeloid leukaemia (LAML), but GRHL3 was not, which is consistent with our earlier conclusion that APOBEC3A is differentially regulated in keratinocytes and myeloid cells." (PMID 39548236, 2025).
anaplastic cancer (1 paper, 2021). "Although induction of differentiation may not be expected in anaplastic cancer cells, we found de novo expression of FOXA1 by IHC analysis in GRHL3-expressing T24 cells when incubated in organ culture." (PMID 33803949, 2021).
bladder tumors (1 paper, 2024). "Significance was also missed for luminal UC; however, none of the luminal bladder tumors characterized by low GRHL3 mRNA expression presented an event." (PMID 38429970, 2024).
Brachycephaly (1 paper, 2016). An abnormality of skull shape characterized by a decreased anterior-posterior diameter. "Overall, the heads of Grhl3−/− embryos appeared shorter, and displayed features highly consistent with human brachycephaly." (PMID 27756203, 2016).
brain cancer (1 paper, 2022). A primary or metastatic malignant neoplasm affecting the brain. "IRF6 was not detectable in 4/5 brain cancer cell lines tested, while GRHL3 levels were variable, ranging from not detectable (e.g., Hs683, T98G) to high expression in LN319." (PMID 36457487, 2022). "We also screened a panel of brain cancer cell lines for IRF6 and GRHL3." (PMID 36457487, 2022).
craniosynostosis (1 paper, 2016). Craniosynostosis is defined as the premature fusion of one or more cranial sutures leading to secondary distortion of skull shape resulting in skull deformities with a variable presentation. "We have shown by Micro CT and histological techniques that genetic loss of Grhl3 in our mouse model results in closer apposition of the frontal and parietal bones, mimicking the early stages of craniosynostosis which may cause significant problems for the animal were it able to survive postnatally." (PMID 27756203, 2016). "Our findings show that our Grhl3 mice present with increased apposition of the frontal and parietal bones, suggesting that Grhl3 may be involved in the developmental pathogenesis of craniosynostosis." (PMID 27756203, 2016).
diffuse large B-cell lymphoma (1 paper, 2024). "However, GRHL3 can also function as tumor promoter, particularly in colorectal carcinoma and diffuse large B‐cell lymphomas." (PMID 38429970, 2024).
endothelial dysfunction (1 paper, 2015). In vascular diseases, endothelial dysfunction is a systemic pathological state of the endothelium (the inner lining of blood vessels) and can be broadly defined as an imbalance between vasodilating and vasoconstricting substances produced by (or acting on) the endothelium. "Leptin-induced miR21 caused sinusoidal endothelial dysfunction primarily by repressing Grhl3, a protein that has a role in phosphorylating NOS3 and increasing NO bioavailability." (PMID 25658689, 2015).
esophageal cancer (1 paper, 2023). A primary or metastatic malignant neoplasm involving the esophagus. "Esophageal cancer patients with high expression of FOXN1, GRHL3, and HES2, stomach cancer patients with high expression of ONECUT2, thyroid cancer patients with high expression of PAX8, and uterine cancer patients that expressed elevated levels of MECOM had decreased survival." (PMID 37627195, 2023).
head and neck cancer (1 paper, 2022). A primary or metastatic malignant neoplasm affecting the head and neck. "Interestingly, loss of Grhl3 induces spontaneous head and neck cancer in aged mice through loss of its direct target gene, GSK3b." (PMID 35269877, 2022). "Moreover, GRHL3 expression in a subset of head and neck cancer patients induces tumour differentiation through induction of its tumour-specific target gene FLG and this differentiation potentially influences anti-cancer therapy responses and patient prognosis." (PMID 35269877, 2022).
hepatocellular carcinoma (1 paper, 2025). A malignant tumor that arises from hepatocytes. "For instance, GPx4 overexpression can activate PTEN/PI3K/AKT signaling and promoting metastasis via transcriptionally silencing GRHL3 (Grainyhead-like 3) expression in hepatocellular carcinoma." (PMID 39908861, 2025).
hyperopia (1 paper, 2008). A refractive error in which rays of light entering the eye parallel to the optic axis are brought to a focus behind the retina, as a result of the eyeball being too short from front to back. "Five of them were upregulated during induction of hyperopia with positive lenses (DCX, NLGN1, QSER1, TMTC3, and LOC41695) and one was downregulated (GRHL3)." (PMID 18769560, 2008).
neuroblastoma (1 paper, 2021). Neuroblastoma (NB) is the most common solid, extracranial childhood tumor. "We can assume that the oncogenic effects of PAX5 may be associated with its negative regulation of expression of GRHL1 and GRHL3, since GRHL1 has been shown to be a tumor suppressor in neuroblastoma, whereas GRHL3 is a tumor suppressor in head and neck SCC." (PMID 34570823, 2021).
oral cancers (1 paper, 2022). "Why the expression and function of IRF6 and GRHL3 are ambiguous in adenocarcinomas and not in skin and oral cancers is not known yet." (PMID 36457487, 2022). "In skin and oral cancers, IRF6 and GRHL3 have been consistently found to act as tumor suppressors." (PMID 36457487, 2022).
oral squamous cell carcinomas (1 paper, 2024). "The effect of grainyhead‐like transcription factor 3 (GRHL3) on cancer development depends on the cancer subtypes as shown in tumor entities such as colorectal or oral squamous cell carcinomas." (PMID 38429970, 2024).
pancreatic cancer (1 paper, 2021). "Furthermore, analysis of a published clinical dataset (GSE15471) revealed that compared with normal pancreatic tissues, SIRT1 and CUL4B expression increased in pancreatic tumor samples, while FOXO3 and GRHL3 significantly decreased." (PMID 34163012, 2021). "As our studies have shown that the SIRT1/CRL4B complex transcriptionally inhibits GRHL3, we hypothesized that SIRT1 inhibits the differentiation of cancer cells by inhibiting GRHL3 expression, thus promoting the stemness and tumorigenesis of pancreatic cancer." (PMID 34163012, 2021). "SIRT1 or CUL4B knockdown in PANC-1 cells decreased cell invasion potential, which was partially rescued via the co-knockdown of FOXO3 or GRHL3, indicating that the SIRT1/CRL4B complex could promote pancreatic cancer invasion through repression of FOXO3 and GRHL3." (PMID 34163012, 2021).
preeclampsia (1 paper, 2025). Preeclampsia is a hypertensive disorder of pregnancy that is characterized by new-onset hypertension with proteinuria presenting after 20 weeks of gestation, and depending on mild or severe forms may initially present with severe headache, visual disturbances, and hyperreflexia. "Notably, the F11R, NOTCH1, GRHL3, and CLDN14 genes were associated with preeclampsia-associated PTB." (PMID 40625359, 2025).
small cell lung carcinoma (1 paper, 2021). Small cell lung cancer (SCLC) is a highly aggressive malignant neoplasm, accounting for 10-15% of lung cancer cases, characterized byrapid growth, and early metastasis. "GRHL3 is abundantly expressed in small-cell lung cancer and adenocarcinoma with progressive stages and associated with chemotherapy resistance." (PMID 34888136, 2021). "GRHL3 is abundantly expressed and associated with chemoresistance in progressive stages of adenocarcinoma and small-cell lung cancer." (PMID 34888136, 2021).
tongue SCC (1 paper, 2025). "Among those cell lines profiled by the CCLE, APOBEC3A and GRHL3 mRNA levels were highest in BICR6 and BICR22; lines derived from an SCC of the hypopharynx and from a lymph node metastasis from a tongue SCC respectively (Fig. EV3B)." (PMID 39548236, 2025).
Umbilical hernia (1 paper, 2025). Protrusion of abdominal contents through a defect in the abdominal wall musculature around the umbilicus. "GRHL3 belongs to the Grainyhead-like (GRHL) transcription factor family and plays a regulatory role in cell proliferation and apoptosis, QTL(QTL:284953) in GRHL3 gene sequence showed a significant association with susceptibility to umbilical hernia in pigs." (PMID 41465762, 2025).
urothelial bladder cancer (1 paper, 2024). "We showed for GRHL3 a reverse expression in squamous and urothelial bladder cancer subtypes." (PMID 38429970, 2024).